ALB (albumin)
Diseases named in the same sentence as ALB in open-access papers (continued):
Sharing a sentence is not in itself a finding about the gene and the disease.
infection (continued). "SMC treatment could restore the ALT, AST, ALP, TP, albumin, creatinine, and uric acid levels toward the normal levels as measured on the 7th and 14th day after infection, revealing the protective effect of SMC, particularly the high dose, which showed a higher protection than diclazuril." (PMID 35071376, 2021). "The albumin/globulin ratio has been documented to be a good indicator of health and response to diseases; hence, the decreased albumin/globulin ratio in pigeons and chickens postinfection/exposure in this study is indicative of immune response to the vvIBDV infection." (PMID 34150893, 2021). "Similarly, albumin concentrations were found to be increased during infection in early pregnancy." (PMID 34710198, 2021). "Moreover, targeted application of nutritional support treatment before surgery, so that patients better tolerate surgery, so albumin and hemoglobin have not become a risk factor affecting surgical site infection." (PMID 33243159, 2020). "However, CART has many advantages that are not reflected in the price, such as no risk of infection peculiar to blood products due to the use of the patient’s own ascites, and recovery of globulin as well as albumin." (PMID 33050943, 2020). "Collectively, the inverse relationship between globulin and albumin in response to inflammation and infection functions to dramatically decrease the A/G ratio, suggesting that the A/G ratio is strongly representing the inflammatory status and infection of our body." (PMID 33028348, 2020). "Another limitation was the small sample size, which may have resulted in the inability to determine significant associations between changes in BMI, prealbumin, and albumin in the presence and absence of inflammation in the different infections." (PMID 30065944, 2018). "Moreover, as the infection became more severe the albumin levels decreased significantly." (PMID 29995751, 2018). "However, changes in protein and albumin levels that occur in ICU patients may lead to unpredictable alterations in the free fraction of the drug that is active at the site of infection." (PMID 27796647, 2017). "Besides IL-6, acute-phase proteins such as C-reactive protein (CRP), and negatives such as albumin and pre-albumin, may be useful as predictors of post-operative infection." (PMID 21668975, 2011). "In school-children, raised urine-albumin concentrations (>40 mg/L) were associated, albeit non-significantly, with prevalence of infection (OR = 3.1, P = 0.070), but more specifically and significantly with the prevalence of micro-haematuria (OR = 76.7, P<0.0001)." (PMID 19806223, 2009). "Although NNIS scores, in association with other acute-phase proteins such as CRP, albumin and prealbumin, and with IL-6, were not the most effective tool, they may enable more accurate prognoses for postoperative infection." (PMID 17505683, 2007). "While CGF provides immediate effects, ALB-CGF prolongs release and ALB-CGF-SNP supports long-term bioactivity, making the latter a promising option for scaffold stability and infection control." (PMID 41612296, 2026). "All viruses were propagated on MDCK II cells in infection MEM (MEM supplemented with 1% Penicillin/Streptomycin (P/S), 0.2% (v/v) bovine serum albumin (BSA) (35%), 0.01% MgCl2, 0.01% CaCl2)." (PMID 39976482, 2025). "In this study, a novel inhaled PMB-loaded albumin nanoparticles (PEG-pHSA@PMB) capable of penetrating airway mucus and responding to the infection microenvironment is constructed." (PMID 40104651, 2025). "Virus dilutions were prepared in infection PBS (PBS supplemented with 1% P/S, 0.2% (v/v) bovine serum albumin (BSA) (35%), 0.01% MgCl2, 0.01% CaCl2)." (PMID 39976482, 2025). "CRP, procalcitonin, leukocyte number, thrombocytes, HDL, LDL, bilirubin, albumin, creatinine, MELD score, and AST of genotype 3 infection were similar to other genotypes (p > 0.05 for all)." (PMID 41301814, 2025).
infection (continued). "Before infection at an MOI of 7, the monolayer integrity was verified by diffusion of less than 4% of added fluorescent albumin." (PMID 39727396, 2025). "The virus was detected in the lungs of mice after 48 h post-infection and it induced alterations of lung wet:dry ratio and BAL albumin and LDH levels, in line with our previous publications." (PMID 41155369, 2025). "Albumin, a known marker of lung damage, was measured in bronchoalveolar lavage fluid (BALF) day 4 of infection and was decreased following anti-CD44 treatment." (PMID 41279061, 2025). "Till week 10 post-infection, sera levels of these markers showed significant alterations as the infection progressed, especially in the levels of AST with changes also in the levels of albumin and GGT." (PMID 41358489, 2025). "The lymphocyte and albumin levels used in the PNI calculation can be influenced by various factors, including infection, malignancy, and medication use." (PMID 41234452, 2025). "Treatment with 20 or 40 mg/kg BW probenecid or 20 mg/kg BW probenecid and amoxicillin increased the ALB and LDH level and reduced the phosphorus (P) level compared with the infection group (p < 0.05)." (PMID 40305201, 2025). "Infection-related composite indices were also increased, with a CRP/albumin ratio of 8.70 ± 11.97, neutrophil-to-lymphocyte ratio 3.56 ± 3.06, and ESR × CRP 4228.14 ± 2246.19." (PMID 41300930, 2025). "The Neutrophil Percentage-to-Albumin Ratio (NPAR) is a blood biochemical marker that reflects the ratio of neutrophils to albumin, serving as an indicator of inflammation, infection, and nutritional status in patients." (PMID 41195013, 2025). "Mice treated with the CRL1505 strain before poly(I:C) stimulation and the infection with pneumococci had significantly lower lung bacterial cell counts, BAL protein, and albumin concentrations and BAL LDH activity." (PMID 39766307, 2024). "The severe infection and tissue damage of Ifngr1-/- mice were evidenced by the aberrant levels of TP, GLOB and ALB." (PMID 38743761, 2024). "Upon analysis, factors that significantly differed between the two groups included concomitant infection, a higher MELD score, lower serum albumin levels, and higher total bilirubin levels." (PMID 38196479, 2024). "At 50–100 mg/kg, baicalin increased the levels of ALB, ALP, GLU, IP, HDL-C and LDL-C and reduced BUN compared to those in the infection group from 24 to 72 h." (PMID 39075542, 2024). "Post-infection, correlations were lost except between BI and ESR, and decreased albumin levels were found." (PMID 39846571, 2024). "These factors encompassed complications; locations of infection; the history of amputation; vascular CTA; levels of albumin, creatinine, and cholesterol; counts of white blood cells; hemoglobin levels; and interleukin-6 levels." (PMID 39735416, 2024). "The levels of T-Bil, AST and D-Bil were significantly upregulated, whereas those of ALB, TC, GLU, HDL-C, LDL-C, γ-GT and CK were downregulated in the infection group compared to the control group (p < 0.05)." (PMID 38582846, 2024). "When the piglets were infected with G. parasuis for 24 h to 72 h, the levels of ALB, ALT, ALP, TC, TG, GLU, Ca, IP, HDL-C and LDL-C were significantly decreased, and BUN was increased in the infection group compared to the control group." (PMID 39075542, 2024). "The neutrophil percentage-to-albumin ratio (NPAR) is a novel measure of systemic inflammation and infection." (PMID 38561807, 2024). "PAR is an index based on serum PCT and ALB levels that are calculated as the PCT level divided by the ALB level and can indicate both the body infection/inflammation and nutritional status." (PMID 36908271, 2023). "Lower serum albumin and higher hs-CRP levels in group 1 patients were evidence of ongoing subclinical inflammation and/or infection status." (PMID 38092856, 2023).
infection (continued). "The rest of the parameters, such as albumin, TB, LDH, and D-dimer, were slightly higher in the initial stage of the infection but the decreasing trend was low; therefore, they cannot be considered helpful in predicting the disease severity." (PMID 36968904, 2023). "Two days after the pneumococcal challenge, the resistance to the infection was evaluated by the determination of lung and blood bacterial cell counts, and BAL albumin content and LDH activity." (PMID 37958756, 2023). "Confirmation of our results might suggest that a decrease in albumin, which has excellent predictive abilities regarding mortality in patients classified as lower risk (SOFA 0–1, 2–3), is a reason to suspect the presence of infection-induced microvascular changes." (PMID 37240554, 2023). "Exposure to HTP and EC exacerbated the accumulation of infection-induced total proteins in the BAL at all time points (p < 0.05) and albumin levels at 4 and 12 h following acute challenge compared to air (p < 0.01)." (PMID 37907902, 2023). "In order to study the effect of IV infection on albumin uptake in MLE-12 cells, we inoculated the cultured cells with IV at a multiplicity of infection (MOI) of 1 and control (mock infection) for 24 h." (PMID 37727782, 2023). "The GP-Ni-Cda2 vaccine was shown to be comparable to our previous approach utilizing mouse serum albumin (MSA) and yeast RNA trapping of Cda2 in GPs in a mouse infection model." (PMID 37242632, 2023). "The thick albumin height of both DMV/1639 IBV-infected and Mass IBV-infected groups was significantly (p < 0.05) less than the control group post-infection." (PMID 38313768, 2023). "Our findings corroborate that GCS, MVT, albumin, CRP, smoking, and DCI are important predictors of postoperative infection and enable physicians to make informed decisions and implement appropriate clinical interventions to reduce the risk of POP." (PMID 37745673, 2023). "This study reaffirms the role of albumin in wound healing and adds to the building evidence on the role of preoperative albumin and WBC count in surgical site infections." (PMID 36357432, 2022). "Many of albumin's proposed immunomodulatory effects are linked to its ability to bind pathophysiological ligands, and we suggest that the lack of any effect of targeted albumin on infection outcome is because of its inability to improve circulating albumin binding capacity." (PMID 35333783, 2022). "These variables were multi-space involvement, gas formation, primary regions of infection, dyspnea, neutrophil count, PLR, and albumin level." (PMID 35321647, 2022). "The majority of participants who achieved HBsAg seroclearance were also taking antivirals (specifically IFN), had longer HBV duration since infection, and had the highest levels of ALT, AST, DBIL, ALB and GGT, but lower level of HBV DNA." (PMID 36304473, 2022). "After controlling for sex, age, infection, proteinuria, SBP, FFA, BMI, TCHO, TG, LDL, HDL and albumin and test results using the PSM approach, the AKI group still showed elevated FFA levels (0.39 mmol/L vs. 0.31 mmol/L, p = 0.006)." (PMID 35912916, 2022). "First, once patients with COPD suffer acute exacerbations, they usually suffer from infection and the inflammatory response will accelerate the process of proteolysis and the BUN levels will be elevated due to lower albumin levels in patients." (PMID 36522751, 2022). "By Days 5 to 7, a number of biomarkers were available as evidence for infection including RNA copy number by qRT-PCR, abnormal clinical chemistry values (CRP, ALT, GGT, ALB), increased clotting time, and changes in cytokines/chemokines." (PMID 36298588, 2022). "In line with other studies, our study showed that serum blood levels of many of these biomarkers such as CRP, blood urea, total bilirubin, CRE, ALP, albumin and LDH increase significantly with infection exacerbation." (PMID 36614820, 2022).
infection (continued). "Based on these findings, we developed a logistic regression model based on blood levels of creatinine, albumin, and CRP, as well as alcoholic etiology that predicts infection with higher accuracy than any individual laboratory parameter or the APACHE II score." (PMID 36057565, 2022). "Those with HBsAg loss were predominantly male, urban employees, taking antiviral treatments (specifically IFN), had a longer HBV duration since infection, and had higher levels of ALT, AST, DBIL, ALB, GGT and LSM." (PMID 36304473, 2022). "The biomarkers associated with an acute infection (Hp, albumin, PON-1 and ADA) are related to previously reported molecular biomarkers in the testicular parenchyma of infected bulls and could help in the diagnosis of early infections and complement IgM detection." (PMID 34551803, 2021). "Haptoglobin was increased, whereas albumin and PON-1 showed a decrease in experimentally infected cattle, and peaks were detected during the first month post-infection." (PMID 34551803, 2021). "In this study, the clinical risk score consisted of 7 features that were independent predictors for airway management in patients with DNSA, including multispace involvement, gas formation, dyspnea, primary region of infection, NEUT%, PLR, and albumin." (PMID 34016187, 2021). "Continuous 4% HAS was effective in reducing healthcare-related infections compared with 20% HAS intermittently (2 vs. 13 episodes; p = 0.002), although circulating concentrations of serum albumin reached similar levels." (PMID 33925831, 2021). "Haptoglobin, albumin, PON-1 and ADA were identified as the biomarkers that showed changes of higher magnitude in the acute phase of the infection, whereas high total protein and globulin values were found in chronically infected cattle." (PMID 34551803, 2021). "This seems to be especially so among older type-2 diabetic patients, those with more than one comorbidity and infection at presentation, those with higher SOFA score and those with lower serum albumin at admission." (PMID 33656122, 2021). "Neutrophil percentage-to-albumin ratio (NPAR) is a novel indicator of systemic inflammation and infection." (PMID 34566849, 2021). "Previous studies have shown that the liver function indexes were related to seral TP, ALB, AST, ALT, and LDH, and changed obviously on day 4 post-infection (dpi)." (PMID 33708811, 2021). "Haptoglobin, albumin, PON-1 and ADA were identified as the most promising biomarkers for the acute phase of the infection." (PMID 34551803, 2021). "Other infection event predictors included a history of CVD, usage of central venous catheter, decreased levels of hemoglobin, albumin, prealbumin, creatinine, and uric acid, and increased serum levels of hsCRP, NT-proBNP, ferritin, and globulin." (PMID 33815398, 2021). "It was also observed that L. rhamnosus CRL1505 was able to significantly reduce BAL albumin and LDH values in ELP-treated infant mice after the infection with RSV." (PMID 33133080, 2020). "The serum total protein, albumin, AST, ALT, GGT, and creatinine were within the physiological range up to 1 month post-infection." (PMID 32367945, 2020). "Biochemical markers of infection and inflammation (elevated CRP and decreased serum albumin levels) and clinical scores of disease severity (elevated APACHE II and SOFA scores) were significant indicators of low plasma glutamine levels." (PMID 32028696, 2020). "The most pronounced changes in nitrogen profile which involved total proteins (TP), albumin (ALB) and urea, were observed on day 7 post infection in the infected group supplemented with fossile additive (IC)." (PMID 29627914, 2019). "Patients with a CRP/ALB ratio > 20% had a longer duration of hospitalization and higher rates of poor kidney function, infection, and re-transplantation due to graft failure, as well as higher overall mortality, than those with a CRP/ALB ratio ≤ 20%." (PMID 31821367, 2019).
infection (continued). "In patients with inflammation and infection, CRP levels usually increase, and albumin levels are expected to decrease." (PMID 31803551, 2019). "Of nine biochemical parameters assessed, only significant differences between groups were detected in serum albumin (ALB) and blood urea nitrogen (BUN) at day 4 post-infection." (PMID 29467018, 2018). "Therefore, we hypothesized that infusing albumin in hospitalized AD/ACLF patients with a serum albumin value less than 30 g/L with a target to increase this value to 35 g/L or higher would improve immune function, prevent new infections, and thus improve mortality." (PMID 28911947, 2018). "The combination of albumin and CRP measurements resulted in the most improved predictive power for cardiovascular death in patients on HD and for infection-related death in patients on PD." (PMID 29494637, 2018). "Moreover, ACT production was increased in B. pertussis after exposure to serum, to calcium and to albumin, which led the authors to speculate that recognition of albumin may be the basic mechanism by which B. pertussis recognizes the host and establishes infection." (PMID 30245672, 2018). "Heterophils decreased ALB and FN1, and released MMP9 to enable their translocation to the site of infection." (PMID 28623956, 2017). "HE, suspicion of infection, baseline and average daily changes of serum TBiL, INR, serum albumin and blood neutrophils percentage were independent prognostic factors for 30-day mortality." (PMID 29312583, 2017). "The data showed that Alexa488-conjugated bovine serum albumin (Alexa488-BSA) was detectable inside DENV2-infected cells and its level was progressively increased during 48-h post-infection." (PMID 27546060, 2016). "Quantifying albumin levels BAL is a good measure of lung damage, thus we examined this during the course of infection." (PMID 27177221, 2016). "The expression of mRNAs for Cadherin, Albumin, GstA4 and AFP were significantly increased 20 and 40 days after the first infection and those for MaoA and MaoB were augmented to some extent." (PMID 28352551, 2016). "The data revealed that albumin internalization was observed in both mock and DENV2-infected cells, and was significantly increased in DENV2-infected cells at 36 and 48 h post-infection." (PMID 27546060, 2016). "At 12 hr post-infection, only background levels of FITC-albumin were detected in the blood of mice infected with either PA99Sbla or PA99null." (PMID 26090668, 2015). "In comparison with control animals that received human albumin, mice that received HMGB1 by the intratracheal route showed a significant increase of bacilli burdens after one week of infection." (PMID 26201072, 2015). "However, it is known that P. aeruginosa also has a metabolic requirement for haem and iron, which the organism would need to establish an infection in an environment where the haem availability may otherwise be restricted by the host via sequestration by serum albumin and haemopexin." (PMID 25706529, 2015). "The use of a ratio between CRP and albumin would provide a variable capable of merging the information provided by CRP and albumin into an index that correlated positively with infection, i.e., a higher ratio indicates higher inflammatory status." (PMID 23555017, 2013). "We also evaluated our data to ascertain the role of infections, BUN, albumin and glucose levels in the induction of diaphragm weakness in mechanically ventilated patients." (PMID 23786764, 2013). "Genes involved in fatty acid transport, albumin (ALB), myosin (MYO1B), and the thrombospondin receptor (CD36), were up-regulated during infection." (PMID 19216742, 2009). "A septic screen including an ascitic tap (sent for white cell/polymorph count (PMN) and culture, protein and albumin) should be performed to rule out infection, irrespective of inflammatory markers." (PMID 41270866, 2025).